E2F7 (E2F transcription factor 7)
Diseases named in the same sentence as E2F7 in open-access papers (continued):
Sharing a sentence is not in itself a finding about the gene and the disease.
colon cancer (9 papers, 2017 to 2024). "Our findings disclosed that the expression of E2F3 had an association with colon cancer stage, meanwhile the expression of E2F7 in colon cancer tissues were significantly increased in patients with colon cancer." (PMID 32117628, 2020). "Herein, we aimed to explore how miR-199b influences colon cancer and to characterize its underlying molecular mechanism associating with E2F transcription factor 7 (E2F7)." (PMID 33489876, 2020). "Based on the gain- and loss-of-function approaches, the cellular functions of colon cancer cells by the E2F7-regulated miR-199b/USP47/MAPK axis were assessed." (PMID 33489876, 2020). "Therefore, it suggested an upregulated E2F7 in colon cancer tissues, which was associated with low survival rate of patients." (PMID 33489876, 2020). "Analysis using the GEPIA2 database also suggested upregulation of E2F7 expression in colon cancer tissues." (PMID 33489876, 2020). "In the subsequent experiments, we found promotion of E2F7 on the progression of colon cancer through its inhibition on miR-199b expression." (PMID 33489876, 2020). "A previous literature reported the possible involvement of E2F7 in the colon cancer initiation and progression." (PMID 33489876, 2020). "Our findings reveal the pro-oncogenic effect of E2F7 on colon cancer development, highlighting E2F7 as a novel target for therapeutic strategy for colon cancer." (PMID 33489876, 2020). "All in all, the results of this study revealed that E2F7 inhibited miR-199b to enhance the development of colon cancer by targeting USP47." (PMID 33489876, 2020). "Assays of RT-qPCR, Western blot, and immunohistochemistry were utilized to detect the expression of E2F7 in the tissue samples collected from 30 patients diagnosed with colon cancer." (PMID 33489876, 2020). "E2F7 expression examined by RT-qPCR showed an enhancement in the tumor tissue samples from 30 patients with colon cancer." (PMID 33489876, 2020). "As Kaplan–Meier survival analysis revealed, the colon cancer patients with high expression of E2F7 had a lower survival rate in." (PMID 33489876, 2020). "Meanwhile, immunohistochemistry revealed an increased expression of E2F7 protein in the colon cancer tissues." (PMID 33489876, 2020). "The most downregulated gene was transgelin, an actin-binding protein that increases metastatic potential of colon cancer cells, followed by asparagine synthetase and the transcription factor E2F7." (PMID 28161520, 2017). "For instance, E2F7 binds the putative promoter region of the miR‐199b gene and significantly repressed the expression of this tumor‐suppressing miRNA in colon cancer, which leads to the increase in its target USP47, and sequentially enhances the MAPK signaling pathway and facilitates tumor progress." (PMID 35924788, 2022). "Moreover, the E2F7 expression was evaluated in common colon cancer cell lines, among which the LOVO colon cancer cells with the lowest E2F7 expression detected was selected for overexpression experiments." (PMID 33489876, 2020). "Additionally, E2F3, E2F4, E2F7 and E2F8 were significantly associated with the stages of colon cancer." (PMID 32117628, 2020). "In the current research, the E2F family member E2F7 promoted the development of colon cancer." (PMID 33489876, 2020). "Our studies indicated that the deregulation of E2F1, E2F2, E2F3, E2F5, E2F7 and E2F8 in colon cancer tissues might play a vital role in colon cancer oncogenesis, which could be promising diagnostic biomarkers for LUAD." (PMID 32117628, 2020). "A prior study revealed that E2F7 promoted the development of colon cancer." (PMID 33489876, 2020). "Besides, the influence E2F7 has on CD133+ colon cancer stem cells was examined, finding results consistent with those from ALDH1+ cells." (PMID 33489876, 2020). "It was identified that E2F7 are expressed highly in the collected colon cancer tissues." (PMID 33489876, 2020). "E2F7 is among the potential targets for molecular-based treatment of colon cancer patients." (PMID 33489876, 2020).
colon cancer (continued). "Our initial results showed a high level of E2F7 in colon cancer tissues, while the inhibitory effect of E2F7 silencing was found on the production of ALDH1+ and the antagonistic effects of ALDH1+ cells on 5-FU treatment and oxidative stress in colon cancer tumor stem cells." (PMID 33489876, 2020). "Furthermore, the sphere formation assay revealed that E2F7 knockdown attenuated the stemness of colon cancer tumor stem cells." (PMID 33489876, 2020). "In addition, E2F7 is highly expressed in HCC and colon cancer and can promote stemness in these cancers, suggesting that E2F7 may be a novel therapeutic target for HCC and colon cancer." (PMID 34476219, 2021). "In addition, the expression of E2F3, E2F4, E2F7 and E2F8 were significantly associated with tumor stages and overall survival of the patients with colon cancer, suggesting that they may serve as potential therapeutic targets for colon cancer." (PMID 32117628, 2020). "Thus, we speculated that promotion of E2F7 expression would occur in ALDH1+ colon cancer stem cells." (PMID 33489876, 2020). "Additionally, miR-520a could regulate inflammatory reactions by targeting E2F7 in colon cancer." (PMID 32117628, 2020). "E2F7 silencing reduced the production of ALDH1+ and CD133+ colon cancer stem cells and antagonized the effects of 5-fluorouracil (5-FU) treatment." (PMID 33489876, 2020). "All in all, E2F7 silencing decreased the proportion of ALDH1+ and CD133+ colon cancer tumor stem cells." (PMID 33489876, 2020). "In colon CSCs, E2F7 was found to transcriptionally inhibit miR-199b expression to promote USP47 expression, thereby increasing colon CSC stemness and accelerating the occurrence of colon cancer." (PMID 34476219, 2021). "However, the relationship among E2F7, miR-199b, and USP47 in colon cancer is scantly reported in the literature." (PMID 33489876, 2020). "Thus, we conducted investigation on the correlation among E2F7, miR-199b, and USP47 and their effects on colon cancer stem cell activity." (PMID 33489876, 2020). "Our study implied that E2F3, E2F4, E2F7 and E2F8 are potential targets of precision therapy for patients with colon cancer while E2F1, E2F2, E3F3, E2F5, E2F7 and E2F8 are potential biomarkers for the diagnosis of colon cancer." (PMID 32117628, 2020). "The results demonstrated that the expression levels of E2F3, E2F4, E2F7 and E2F8 displayed significant correlation with the tumor stage in patients with colon cancer while other members in E2F family in normal group and tumor group did not significantly differ." (PMID 32117628, 2020). "Therefore, we are convinced that present results show that E2F7 suppressed the miR-199b expression and promoted USP47 to stabilize MAPK proteins, thereby contributing to colon cancer development." (PMID 33489876, 2020). "Besides, the silencing of E2F7 was observed to suppress the oxidative stress, proliferation, migration, as well as invasion of ALDH1+ cells in vitro and tumorigenesis of colon cancer cells in vivo." (PMID 33489876, 2020). "Additionally, our findings also revealed that E2F7 promoted MAPK stability to enhance cell proliferation, invasion, and migration in colon cancer." (PMID 33489876, 2020). "In conclusion, our study reported that E2F7 downregulated the expression of miR-199b, leading to the upregulation of the miR-199b target USP47 that stabilized MAPK, promoting colon cancer stem cell activity, thereby accelerating the development and progression of colon cancer." (PMID 33489876, 2020). "Therefore, although TF E2F7 display opposite regulation effect on GFRA1 when comparing with NR3C2 and NR3C1, it did not have a competitive role with them in colon cancer." (PMID 32849837, 2020).
lung adenocarcinoma (9 papers, 2018 to 2025). A carcinoma that arises from the lung and is characterized by the presence of malignant glandular epithelial cells. "CircPRKCI serves as a ceRNA to accelerate tumorigenesis of lung adenocarcinoma by binding to both miR-545 and miR-589, subsequently suppressing the downstream gene E2F7." (PMID 35654787, 2022). "In view of this, we conducted this study to explore the expression of E2F7 in lung adenocarcinoma (LUAD) and analyze its correlation with clinical parameters, diagnostic and prognostic value of LUAD patients." (PMID 35984189, 2022). "Although our study provides a new method to explore the relationship between E2F7 and the prognosis of lung adenocarcinoma, it still has many limitations." (PMID 35984189, 2022). "Therefore, we conducted this study to explore the prognostic value of E2F7 for lung adenocarcinoma (LUAD) patients." (PMID 35984189, 2022). "Besides, circPRKCI acts as a ceRNA to promote proliferation and tumorigenesis via sponging miR-545 and miR-589 and relieve the inhibition on the target gene E2F7 in lung adenocarcinoma." (PMID 32497020, 2020). "The results indicated that the expression levels of E2F1, E2F2, E2F3, E2F5, E2F6, E2F7, and E2F8 were higher in lung adenocarcinoma and squamous cell lung carcinoma tissues than in lung tissues, whereas and the expression level of E2F4 was lower in the former than in the latter." (PMID 29754146, 2018).
pancreatic cancer (8 papers, 2020 to 2025). "E2F7 has been reported to be highly expressed in pancreatic cancer tissues, and higher expression of E2F7 was associated with the poorer prognosis." (PMID 36612299, 2023). "These previous studies and our study show that various ncRNAs are associated with regulating E2F7, which may play an important role in the malignant phenotype of pancreatic cancer." (PMID 36612299, 2023). "Xu and Qi suggested that miR-10b inhibits invasion by migration of pancreatic cancer cells by regulating E2F7 expression, and that the high expression of E2F7 is associated with poor prognosis." (PMID 36612299, 2023). "The prognostic value of E2F7 in pancreatic cancer was also emerged, however, the role of E2F7 in pancreatic cancer still remains largely unknown." (PMID 35201478, 2021). "The lncRNA CASC19 developed pancreatic cancer with CASC19/miR-148b/E2F7 axis." (PMID 35047414, 2021). "In addition to E2F7, other potential targets of miR-26a were also predicted and they may also partially contribute to the function of miR-26a in pancreatic cancer, which deserves further investigation." (PMID 35201478, 2021). "The involvement of these targets of E2F7, such as BRCA1, CDC25A, CDC6 in pancreatic cancer deserves further investigation." (PMID 35201478, 2021). "Interesting, we found six genes E2F7, CDC6, MMP14, PLK1, VASP and PKM2 were significantly correlated with the prognosis of patients with pancreatic cancer in TCGA, GSE71729, GSE78229 and GSE79668 datasets." (PMID 32950968, 2020). "Similar to this, E2F7 exerts an actively transcriptional effect, but not repressively as general, was found in pancreatic cancer, and promotes tumor cell proliferation by efficient enhancement of VEGFa transcription." (PMID 35924788, 2022). "In pancreatic cancer (PC), CASC19 could facilitate malignant growth and metastasis of PC via miR-148b/E2F7 ceRNA axis with sponge activity." (PMID 34594376, 2021).
esophageal cancer (7 papers, 2018 to 2024). A primary or metastatic malignant neoplasm involving the esophagus. "We searched the GEPIA database to check the expression correlation between these key molecules in 182 esophageal cancer tissues and the results revealed a positive expression correlation between E2F7 and QKI, E2F7 and TNPO1, QKI and TNPO1." (PMID 35840974, 2022). "Tumor suppression is reached by the regulation of E2F7 proteins in gallbladder and esophageal cancer, and GRP78 in renal carcinoma." (PMID 35203624, 2022). "Interestingly, E2F7 is upregulated in esophageal cancer, as evidenced by GEPIA database and a previous study." (PMID 35840974, 2022). "Based on hTFtarget database, HIF-1α is a transcriptional factor for E2F7, which may explain the hypoxia-induced E2F7 in esophagus cancer cells." (PMID 35840974, 2022). "Interestingly, we found that E2F7 was notably highly expressed in esophageal cancer." (PMID 35840974, 2022). "Hypoxia induces the upregulation of E2F7, which transcriptionally activates QKI in esophageal cancer cells." (PMID 35840974, 2022). "Our experimental results revealed that TNPO1 was upregulated in esophageal cancer tissues and showed positive expression correlation with QKI and E2F7." (PMID 35840974, 2022). "In addition to HIFs, hypoxia also induced E2F transcription factor 7(E2F7) to increase the transcription of splicing factor quaking (QKI), which promotes the biogenesis of circBCAR3, a circular RNA highly expressed in the esophageal cancer cells." (PMID 37048123, 2023).
liver cancer (7 papers, 2018 to 2024). An epithelial or non-epithelial malignant neoplasm that arises from the liver. "Next, we analyzed the gene expression of E2F7 in formation and differentiation of LCSCs to explore the association between liver cancer stemness and E2F7 level." (PMID 30326936, 2018). "Cellular functional analysis demonstrated that miRNA-302a/d negatively regulates self-renewal capability and cell cycle entry of liver cancer stem cells via suppression of its target gene E2F7 and its downstream AKT/β-catenin/CCND1 signaling pathway." (PMID 30326936, 2018). "As expected, E2F7 overexpression abolished the effects of miRNA-302a/d in liver cancer cell spheroid formation." (PMID 30326936, 2018). "miRNA-302a/d could downregulate the self-renewal ability of liver cancer stem cells and proliferation of liver cancer cells by inhibiting E2F7/AKT/β-catenin/CCND1 signaling pathway." (PMID 36360311, 2022). "First of all, we explored the expression profile of E2F7 specifically in HCC tissues compared with the normal tissues throughout the analysis GSE45114 data set from GEO database and the liver cancer data set from TCGA database." (PMID 35924788, 2022). "Similarly, overexpressed E2F7 could significantly impact AKT/β‐catenin/CCND1 signaling pathway and promote the liver cancer stem cells to self‐renew and cell cycle entry." (PMID 35924788, 2022).
prostate carcinoma (7 papers, 2020 to 2024). A carcinoma that arises from epithelial cells of the prostate gland. "Additionally, E2F7, regulated by miR-30c, inhibits apoptosis and promotes the cell cycle of prostate cancer cells." (PMID 35531101, 2022). "Inhibition of E2F7 enhanced G1 phase percentage in prostate cancer reducing cellular proliferation." (PMID 32660466, 2020). "In short, few studies have focused on the function of these three E2Fs in PCa, and the roles of E2F4, E2F7, and E2F8 in prostate cancer remain to be explored." (PMID 35531101, 2022). "MiRNA-30 c could suppress prostate cancer survival by targeting KRAS Proto-Oncogene, E2F Transcription Factor 7 (E2F7), or alternative splicing factor/splicing factor 2 (ASF/SF2)." (PMID 34503377, 2021).
squamous cell carcinoma (7 papers, 2011 to 2024). A carcinoma arising from squamous epithelial cells. "RACGAP1 was also found to be a downstream effector of E2F7-dependent resistance to doxorubicin and a prognostic for OS in squamous cell carcinoma." (PMID 36430577, 2022). "E2F7 overexpression has been identified as a prominent hall mark of squamous cell carcinomas (SCC)." (PMID 24955216, 2014). "Moreover, we reported that E2F1 and E2F7 were overexpressed in human squamous cell carcinomas approximately 50 fold and 200 fold respectively." (PMID 22272113, 2011). "The interplay between E2F1-stimulated apoptosis and E2F7/8-mediated inhibition of apoptosis is critical to understanding the role of E2Fs in UV-induced skin cancer formation and their potential as drugable targets for treating squamous cell carcinomas or enhancing chemotherapeutic responses." (PMID 22272113, 2011). "In squamous cell carcinoma, RACGAP1 was found to be regulated by the E2F7 transcription factor, and its expression enhanced doxorubicin resistance." (PMID 30866526, 2019).
cervical cancer (6 papers, 2020 to 2023). A primary or metastatic malignant neoplasm involving the cervix. "Next, the inhibitory effect of E2F2 and E2F7 knockdown on cervical cancer cell growth was validated by CCK-8 analysis." (PMID 33061852, 2020). "We found that expression of E2F2 (p < 0.05) and E2F7 (p < 0.01) was significantly upregulated in primary cervical cancer tissues compared with adjacent normal tissues." (PMID 33061852, 2020). "Our findings showed that E2F2 and E2F7 knockdown induced cell cycle arrest in the G0/G1 phase in cervical cancer cells." (PMID 33061852, 2020). "Considering that E2F2 and E2F7 downregulation inhibits proliferation of cervical cancer cells, we performed cell cycle analysis to evaluate the role of E2F2 and E2F7 in cell-cycle distribution." (PMID 33061852, 2020). "Expression levels of E2F2 and E2F7 in cervical cancer tissues were determined by RT-qPCR." (PMID 33061852, 2020). "Thus, E2F2 and E2F7 promote cervical cancer cell proliferation through regulating the cell cycle." (PMID 33061852, 2020). "E2F2 and E2F7 are involved in cell proliferation, migration, and cell cycle in both HPV-positive and HPV-negative cervical cancer cells." (PMID 33061852, 2020). "Finally, in vitro experiments showed that E2F2 and E2F7 are involved in cell proliferation and migration and cell cycle regulation in both HPV-positive and HPV-negative cervical cancer cells." (PMID 33061852, 2020). "We then confirmed these findings using IHC and RT-qPCR at the protein and mRNA level, and using in vitro experiments, showed that E2F2 and E2F7 are involved in cell proliferation, migration, and cell cycle regulation in both HPV-positive and HPV-negative cervical cancer cells." (PMID 33061852, 2020).
endometrial carcinoma (6 papers, 2017 to 2021). A malignant tumor arising from the epithelium that lines the cavity of the uterine body. "Our previous study explored the roles of microRNA-424 (miR-424) in the development of endometrial carcinoma (EC) and analyzed the miR-424/E2F7 axis in EC cell growth." (PMID 29371986, 2017). "Our previous study showed that miR-424 mediated the repression of E2F7 in endometrial cancer cells, suppressing cell proliferation, increasing cell apoptosis and causing cell cycle arrest." (PMID 29371986, 2017). "Knockdown of E2F7 can repress cell growth in endometrial carcinoma." (PMID 34416861, 2021). "A new discovery demonstrated that knockdown of E2F7 repressed endometrial cancer cell growth." (PMID 33637098, 2021). "Our previous results demonstrated that E2F7 is a target of miR-424 in endometrial cancer." (PMID 29371986, 2017). "E2F8, E2F7, and E2F1 were the top three, most-frequently altered genes in endometrial cancer." (PMID 33329696, 2020).
head and neck squamous cell carcinoma (4 papers, 2019 to 2024). A squamous cell carcinoma that arises from any of the following anatomic sites: lip and oral cavity, nasal cavity, paranasal sinuses, pharynx, larynx, and salivary glands. "Previous studies have shown that the E2F7 protein has a cytoplasmic distribution in 80% of head and neck squamous cell carcinomas but in less than 10% of normal tissues." (PMID 39613162, 2024). "Previous studies indicated that E2F7 is frequently mislocalized to the cytoplasm, representing actionable pathology in head and neck squamous cell carcinomas (HNSCCs)." (PMID 35197448, 2022).